RBP4 (retinol binding protein 4)
Diseases named in the same sentence as RBP4 in open-access papers (continued):
Sharing a sentence is not in itself a finding about the gene and the disease.
Insulin resistance (continued). "For instance, although RBP4 levels correlated with insulin resistance in some type-II diabetes patients, other reports have shown the opposite." (PMID 24609035, 2014). "In states of obesity and insulin resistance, RBP4 is preferentially produced by visceral adipose tissue compared with subcutaneous adipose tissue, and thus it is linked to intra-abdominal adipose tissue expansion." (PMID 24733068, 2014). "Subsequent human studies revealed elevated RBP4 levels in the plasma of subjects with insulin resistance and a positive correlation between RBP4 expression and the magnitude of insulin resistance." (PMID 25479076, 2014). "Increases in the concentration of RBP-4 were also shown to be linked with the increase of some risk factors of CVD, such as increased inflammation and insulin resistance." (PMID 26464853, 2014). "A high level of plasma RBP4 can enhance insulin resistance through inhibition of IRS-1 and activation of phosphatidylinositol 3-kinase (PI3-K) in skeletal muscles." (PMID 24604418, 2014). "RBP4 is an adipokine secreted by adipose tissue and liver and contributes to insulin resistance (IR)." (PMID 25250314, 2014). "Knowing that states of chronic low grade inflammation are associated with increased RBP4 levels, so the explanation could be that altered adipokine together with activation of the inflammatory system could promote the development and progression of cancer independently on insulin resistance." (PMID 25250314, 2014). "In animal models, the overexpression of human RBP4 or the injection of recombinant RBP4 induces insulin resistance in mice, whereas RBP4 knockout mice showed enhanced insulin sensitivity." (PMID 24559154, 2014). "The connection between RBP4 and insulin resistance was more specifically demonstrated with RBP4 transgenic mice and by administering recombinant protein to wild-type mice." (PMID 25479076, 2014). "Regarding the underlying mechanisms, we observed the independent correlation of RBP4 with insulin resistance indices and established markers of inflammation, like hsCRP." (PMID 25142320, 2014). "Remarkably, elevated RBP4 levels were directly correlated with body mass index (BMI), insulin resistance, and impaired glucose homeostasis and were inversely correlated with glucose transporter-4 levels in adipocytes." (PMID 25250314, 2014). "In another study involving patients with diabetes and CAD, RBP4 levels rose in subjects with both conditions, and were rather correlated with TNFa than with markers of insulin resistance." (PMID 25142320, 2014). "For RBP4, relationships with insulin resistance and glucose homeostasis have been controversially discussed." (PMID 24968098, 2014). "It is known that plasma RBP4 concentrations are positively related to insulin resistance, diabetes mellitus type 2, obesity, and a history of GDM." (PMID 24665145, 2014). "In 2005, a study on the genetics of glucose transport protein 4 (GLUT4) identified a new type of adipokine, retinol-binding protein 4 (RBP4), as a contributor to insulin resistance." (PMID 25479076, 2014). "Recent studies in human and animals have shown that both lipocalin-2 and RBP4 are modulators of insulin signaling and their levels are elevated in subjects with obesity, insulin resistance, or type 2 diabetes." (PMID 23799122, 2013). "Retinol-binding protein 4 (RBP4) is a specific carrier protein for retinol; it is associated with variables related to insulin resistance; is involved in inflammation and related to liver function; and its serum level is reduced in critically ill patients." (PMID 23566303, 2013). "The aim of the present study was to investigate the potential effect of ghrelin- and GH-induced insulin resistance on circulating RBP4 concentrations." (PMID 23781325, 2013). "A study reported that high circulating levels of serum RBP4 increased the potential for insulin resistance by blocking insulin signaling in muscle, thus increasing hepatic glucose output." (PMID 24282409, 2013).
Insulin resistance (continued). "Circulating RBP4 is also elevated in several other mouse models of insulin resistance as well as in insulin-resistant humans." (PMID 23840311, 2013). "In conclusion, the correlations of visfatin/Nampt, vaspin, and RBP-4 with insulin resistance are tissue dependent." (PMID 24367155, 2013). "In one clinical trial, serum RBP4 levels correlated with insulin resistance (in obese subjects) and impaired glucose tolerance or type 2 diabetes in nonobese subjects with a family disposition to type 2 diabetes." (PMID 23781325, 2013). "The increase in circulating RBP4 that often precedes the development of systemic insulin resistance is most likely unrelated to inflammatory processes in adipose tissue." (PMID 23460908, 2013). "RBP4, the specific transport protein for retinol, is elevated in the serum prior to the development of apparent diabetes and indicative of insulin resistance across subjects exhibiting a range of metabolic profiles." (PMID 23936766, 2013). "This review article focuses on novel adipokines including visfatin, resistin, apelin, vaspin, and retinol binding protein-4 (RBP-4) and addresses their changes after bariatric surgery and their relationship to insulin resistance." (PMID 23772224, 2013). "For example, RBP4 was discovered from adipose tissue specific GLUT4 knockout mouse to explain strong insulin resistance in this animal model." (PMID 23970879, 2013). "The mechanisms by which ghrelin induces insulin resistance and lipolysis remain to be investigated, and in this report, we have focused on the potential role of RBP4 in ghrelin-induced insulin resistance." (PMID 23781325, 2013). "Like chemerin, RBP4 serves as a biomarker of obesity-related diseases including insulin resistance, dyslipidemia, hypertension, and visceral obesity in both adult and adolescent humans." (PMID 23947536, 2013). "RBP4 has been identified as an adipokine involved in detection of insulin resistance and type 2 diabetes." (PMID 24099047, 2013). "To further investigate how these variables influence RBP4 in pathologies characterized by varying degrees of insulin resistance, we adjusted RBP4 for independent variables." (PMID 24223837, 2013). "Numerous research studies have demonstrated that RBP-4 gene expression levels in visceral adipose tissue are positively correlated with insulin resistance." (PMID 24367155, 2013). "In line with this, when the population was stratified as normal or hypertriglyceridemic, those with higher levels of triglycerides had the highest levels of RBP4, independently of their degree of insulin resistance." (PMID 24223837, 2013). "Since increased RBP-4 plasma levels were shown in GLUT4 knockout mice, many research studies have investigated the relationship between RBP-4 and insulin resistance." (PMID 24367155, 2013). "Retinol-binding protein 4 (RBP4) was originally identified as a signal molecule, which transfers the intercellular signals for insulin resistance." (PMID 23671852, 2013). "Visfatin/Nampt, vaspin, and retinol binding protein-4 (RBP-4) play an important role in insulin resistance." (PMID 24367155, 2013). "The relationship between insulin resistance and tissue adipokines, especially visfatin/Nampt, vaspin, and RBP-4, is not completely understood." (PMID 24367155, 2013). "Since the relationship between RBP4 and insulin resistance was controversial, and impaired β-cell was another important pathogenesis of diabetes mellitus, the relationship between β cell function and RBP4 need to be further studied." (PMID 24160775, 2013). "In this context, growing evidence suggests that RBP4 plays a more important role in lipid metabolism than in insulin resistance." (PMID 24223837, 2013). "RBP4 has been shown to significantly correlate with clinical features relating to insulin resistance and metabolic syndrome, including hyperlipidemia and hypertriglyceridemia." (PMID 23671852, 2013).
Insulin resistance (continued). "We also show that triglycerides are the main independent predictor for determining systemic RBP4 levels, independently of the degree of insulin resistance." (PMID 24223837, 2013). "Plasma RBP-4 levels are positively correlated with insulin resistance in subjects with obesity, impaired glucose tolerance, or type 2 diabetes." (PMID 23772224, 2013). "The increase in circulating RBP4 that often precedes the development of systemic insulin resistance is most likely unrelated to these processes." (PMID 23460908, 2013). "RBP4 inhibits insulin-induced phosphorylation of IRS1 suggesting that adipocyte secreting RBP4 induces insulin resistance." (PMID 23781214, 2013). "RBP4, the inflammatory mediator mentioned previously, induces insulin resistance, further connecting obesity, inflammation, and insulin resistance." (PMID 23050155, 2012). "A likely reason for the insulin resistance is altered RBP4 and adiponectin levels as well as an inability to store additional lipids in the subcutaneous depot during weight gain." (PMID 22992414, 2012). "In pathologic glucose tolerance states (such as obesity, insulin resistance, polycystic ovary syndrome, and cardiovascular disease), RBP-4 concentration has been shown to be elevated." (PMID 22550485, 2012). "Plasminogen activator inhibitor-1, interleukin (IL)-1, IL-6, IL-8, and IL-10, and tumor-necrosis-factor-alpha mediate insulin resistance and are elevated in sepsis, while retinol-binding protein-4 concentrations are significantly reduced in sepsis." (PMID 22272381, 2012). "It has moreover been demonstrated that overexpression of RBP-4 in normal mice increases insulin resistance, whereas genetic disruption of this adipokine increases insulin sensitivity." (PMID 22550485, 2012). "RBP4 is secreted by adipose tissues and hepatocytes, and there are controversial reports regarding the effect of RBP4 on insulin resistance." (PMID 21869928, 2012). "Of these adipokines, retinol binding protein-4 (RBP4) acts as a potential determinant of insulin resistance and plays a role to induce sub clinical inflammation leading to cardiovascular diseases in T2DM." (PMID 23497488, 2012). "RBP4 was highly related to the insulin resistance (IR) and type 2 diabetes mellitus and the serum GLUT4 levels were inversely correlated with the expression of tissue GLUT4 protein." (PMID 24250489, 2012). "Plasma retinol binding protein 4 (RBP4), produced mainly by the liver, has also been shown to be an adipokine, favoring insulin resistance in mice." (PMID 23201837, 2012). "It has been shown that RBP4 is associated with variables related to insulin resistance and diabetic complications; an increased level of plasma RBP4 increases insulin resistance by inhibiting insulin signaling." (PMID 22568928, 2012). "In HIV-infected patients receiving HAART, the serum RBP4 level has been positively correlated with obesity, insulin resistance and dyslipidemia." (PMID 23145084, 2012). "RBP4 is the specific carrier protein for retinol (vitamin A) and has recently been described as an adipokine that contributes to insulin resistance." (PMID 21418657, 2011). "Retinol Binding Protein 4 (RBP4) is an exciting new biomarker for the determination of insulin resistance and type 2 diabetes." (PMID 21479165, 2011). "As a clinical biomarker of insulin resistance and type 2 diabetes, the quantitation of retinol binding protein 4 has gained much interest in the past few years and has been extensively studied and associated with a variety pathologies." (PMID 21479165, 2011). "Yang and Graham showed a strong positive relation between increased serum RBP4 levels and the incidence of type II diabetes and insulin resistance." (PMID 22254074, 2011). "More recently, retinol binding protein-4 (RBP-4), produced by the adipocytes and liver, has been shown to correlate with insulin resistance in Chinese." (PMID 22164267, 2011).
Insulin resistance (continued). "Serum RBP4 correlated positively with the presence of insulin resistance in individuals with obesity, impaired glucose tolerance or type 2 diabetes." (PMID 20932285, 2010). "In animal models of insulin resistance, the expression of RBP4 was strongly induced in adipose tissue, and systemic release of RBP4 appeared to be a crucial signal for the development of systemic insulin resistance." (PMID 20932285, 2010). "We aimed at understanding the potential involvement of RBP4 in the pathogenesis of insulin resistance in critical illness, its regulation in severe systemic inflammation and its potential clinical use as a biomarker in ICU patients." (PMID 20932285, 2010). "• Retinol-binding protein 4 (RBP4) has been suggested to contribute to insulin resistance, a common characteristic of critically ill patients with implications for adverse outcome." (PMID 20932285, 2010). "To understand potential pathophysiological consequences of reduced RBP4 levels in ICU patients, we analyzed associations between serum RBP4 and insulin resistance as well as diabetes." (PMID 20932285, 2010). "Retinol binding protein 4 (RBP4) promotes insulin resistance in mice and is systemically elevated in patients with obesity and type 2 diabetes." (PMID 20932285, 2010). "RBP4, the circulating transporter for vitamin A, has recently been recognized as an important mediator of insulin resistance in mice and humans, but its potential role in sepsis or critical illness is presently a matter being researched." (PMID 20932285, 2010). "Recent studies have shown a new role for RBP4 as a signal that links adipose tissue dysfunction to systemic insulin resistance and type-2 diabetes." (PMID 20307313, 2010). "According to these studies, impaired glucose uptake in adipose tissue results in secondary systemic insulin resistance through release of the adipose-derived serum RBP4." (PMID 19460132, 2009). "Conversely, mice lacking the RBP4 gene show increased insulin sensitivity, and normalizing increased RBP4 serum levels improves insulin resistance and glucose intolerance." (PMID 19460132, 2009). "Serum RBP4 levels correlated with several parameters related to insulin resistance including waist circumference, HOMA index, fasting glucose and triglycerides levels." (PMID 17941908, 2008). "A previous study reported that normalization of circulating RBP4 by synthetic retinoid improves insulin resistance." (PMID 17941908, 2008). "Notably, in a murine model exhibiting diminished testosterone activity, there was a marked increase in RBP4 protein concentrations, potentially linking it to the onset of insulin resistance." (PMID 40405972, 2025). "RBP4 has been involved as a moderator contributing to insulin resistance and metabolic disorders." (PMID 39857718, 2025). "Notably, RBP4 links adiposity and insulin resistance to cancer biology, with its role being more pronounced in individuals with lower BMI due to adipose tissue dysfunction in obesity." (PMID 41007818, 2025). "This association was independent of gender, age, insulin resistance, adiponectin, RBP4, and visfatin." (PMID 40507178, 2025). "In our study, we aimed to determine whether serum RBP4 levels correlate with the magnitude of insulin resistance." (PMID 40951890, 2025). "RBP4 is emerging as an important contributor to various pathologies related to cardiovascular disease, including promoting oxidative stress, apoptosis, and alterations in lipid metabolism and increasing insulin resistance, as already alluded to." (PMID 41515891, 2025). "Elevated serum RBP-4 concentrations have been reported in obesity, insulin resistance, and T2DM." (PMID 41303021, 2025). "Computational docking studies further indicate that UA could interact with the insulin receptor (IR) and retinol-binding protein 4 (RBP4), suggesting a potential role in enhancing insulin receptor signaling and mitigating RBP4-associated insulin resistance." (PMID 41374004, 2025).
Insulin resistance (continued). "Elevated circulating RBP4 levels or increased RBP4 mRNA expression in adipose tissue are consistently found in obese and diabetic individuals, as well as in their first-degree relatives, correlating positively with both adiposity and insulin resistance." (PMID 41303567, 2025). "Furthermore, evidence has demonstrated that retinol-binding protein 4 (RBP4) is crucial for managing insulin resistance." (PMID 40405972, 2025). "Moreover, RBP4 levels in the serum reportedly decrease significantly in diabetic patients after treatment with drugs that improve insulin resistance, such as pioglitazone and rosiglitazone." (PMID 38520616, 2024). "A recent study showed that RBP4 may be involved in hyperuricaemia-induced insulin resistance by inhibiting IRS/PI3K/Akt phosphorylation." (PMID 39698033, 2024). "Taken together, renal function, liver function, vitamin A and other adipokine levels, fat distribution, and adipose tissue dysfunction could also partly explain the inconsistent correlation between RBP4 levels and insulin resistance." (PMID 38520616, 2024). "Moreover, studies in mice have shown that elevated serum levels of RBP4 can induce insulin resistance." (PMID 38966226, 2024). "Retinol-binding protein 4 is involved in the development of i.a. insulin resistance." (PMID 38256272, 2024). "A population-based study revealed that RBP4 levels were associated with insulin resistance in obese, impaired glucose, type 2 diabetic, nonobese, and nondiabetic populations." (PMID 38520616, 2024). "A decrease in TTR may increase free RBP4 levels, promoting insulin resistance during stress responses." (PMID 39498350, 2024). "A subsequent study found that the specific deletion of GLUT4 in adipocytes significantly increased RBP4 levels, which induced the expression of gluconeogenic enzymes in the liver and impaired insulin signalling in the muscle, thereby inducing insulin resistance." (PMID 39698033, 2024). "Increased RBP4 is found in insulin resistance, obesity, and non-alcoholic fatty liver disease." (PMID 38673873, 2024). "Moreover, a genetic study also indicated a role for RBP4 genetic variation in susceptibility to T2DM and insulin resistance, possibly through an effect on RBP4 expression." (PMID 38520616, 2024). "Similarly, our results also found that RBP4 was positively correlated with insulin resistance, so insulin resistance played an important intermediate role in the relationship between RBP4 and CKD." (PMID 39698033, 2024). "The potential mechanisms of action of RBP4 and uric acid remain unclear, and insulin resistance factors may be involved." (PMID 39698033, 2024). "Obese women with polycystic ovary syndrome exhibit higher concentrations of RBP4 in serum compared to normal individuals, often accompanied by features of insulin resistance; the overexpression of RBP4 inhibits the growth and development of pig granulosa cells while promoting apoptosis." (PMID 39518840, 2024). "Increased plasma concentrations of RBP4 are correlated with obesity and insulin resistance, and hepatic depletion of Retsat decreases glycolytic flux and de novo lipogenesis, consistent with decreased expression of these genes contributing to the metabolic phenotype of Fmo5-/- mice." (PMID 37267233, 2023). "A previous study showed that elevation of serum GGT is associated with hepatic steatosis, which contributes to development of insulin resistance by altering the secretion of factors from the liver such as lipids and hepatokines including retinol-binding protein 4 and fetuin A and B." (PMID 36823659, 2023). "Retinol binding protein 4 (RBP4) is a novel adipocytokine that may link obesity and insulin resistance." (PMID 36776154, 2023). "RBP4 is a unique adipocytokine that seem to be link obesity and insulin resistance." (PMID 36776154, 2023). "Moreover, overexpression of RBP4 led to decrease glucose intolerance and increase insulin resistance in mice." (PMID 36776154, 2023).